LAIR2 (leukocyte associated immunoglobulin like receptor 2)
Synonyms: LAIR-2; CD306
Tractability: Antibody: its Gene Ontology location is reachable by antibodies, with high confidence; UniProt places it where antibodies can reach, with medium confidence; UniProt predicts a signal peptide or a membrane-spanning region.
Gene: Protein-coding gene on chromosome 19 (54,497,879 to 54,510,687, forward strand). Ensembl gene ENSG00000167618.
Subcellular location: Secreted
Pathways (Reactome):
Immune System: Immunoregulatory interactions between a Lymphoid and a non-Lymphoid cell
Gene Ontology:
Molecular function: protein binding; immune receptor activity; transmembrane signaling receptor activity
Biological process: immune response-inhibiting cell surface receptor signaling pathway
Cellular component: extracellular region; plasma membrane
Genetic constraint (gnomAD): Loss-of-function variants: 14 observed, 13.59 expected, observed/expected ratio (o/e) 1.03, 90% interval 0.68 to 1.6. The upper end of that interval is the gene's LOEUF score, 1.6, which puts it in group 6 of 6, group 1 being the genes least tolerant of losing a copy. Missense variants: 172 observed, 171.59 expected, observed/expected ratio (o/e) 1, 90% interval 0.88 to 1.14. Synonymous variants: 75 observed, 68.06 expected, observed/expected ratio (o/e) 1.1, 90% interval 0.91 to 1.34.
Homologues: Orthologues: chimpanzee LAIR2 (99% identical), chimpanzee LAIR2 (92% identical). Paralogues in human: LILRA6 (41% identical), LILRB3 (39% identical), LILRA5 (38% identical), LILRB5 (38% identical), LILRB4 (37% identical), LILRA1 (35% identical), LILRA2 (34% identical), LILRB1 (34% identical), IGSF1 (33% identical), LILRA4 (33% identical), LILRB2 (32% identical), NCR1 (29% identical), and 13 more.
Diseases named in the same sentence as LAIR2 in open-access papers:
LAIR2 is named in the same sentence as 32 diseases in open-access papers, as found by Europe PMC text mining. Sharing a sentence is not in itself a finding about the gene and the disease. The quoted sentences say what the papers report.
autoimmune thyroid disease (4 papers, 2018 to 2023). Inflammatory disease of the thyroid gland due to autoimmune responses leading to lymphocytic infiltration of the gland. "LAIR2 is elevated in the serum and synovial fluid of patients with rheumatoid arthritis and in the serum of patients with autoimmune thyroid disease, suggesting a role for LAIR2 at sites of inflammation." (PMID 35008369, 2021). "In this example, highly expressed LAIR2 can out-compete LAIR1 for binding sites thereby resulting in a more activated phenotype, as evidenced by the correlation of autoimmune thyroiditis with elevated expression of LAIR2." (PMID 29931472, 2018).
lung carcinoma (4 papers, 2021 to 2023). "Overexpression of LAIR2 in lung cancer could increase immune infiltration levels and rescue exhaustive CD8+ T cells’ function." (PMID 33841428, 2021). "Indeed, in a murine model of lung cancer, the overexpression of LAIR2 within tumor cells was found to rescue collagen-induced inhibition of anti-tumor CD8+ T cells and response to anti-PD1 therapy, resulting in tumor reduction." (PMID 35008369, 2021). "To understand the role of LAIR2 in lung cancer, we performed GO analysis, querying biological processes within our bulk transcriptomic dataset and found that the most significant gene ontologies associated with LAIR2 expression were involved in immune-related functions." (PMID 35008369, 2021). "Furthermore, gene set enrichment analysis (GSEA) using curated gene sets with biologically defined functions in lung cancer immunity showed that a high expression of LAIR2 was associated with “T cell signatures of lung cancer” and “exhaustion”, but not resident memory T cells." (PMID 35008369, 2021). "In addition, the introduction of the LAIR-1 decoy protein, LAIR-2, sensitizes previously resistant lung tumors to programmed death-1 (PD-1) blockade, indicating the potential of LAIR-1 as an alternative marker for anti-PD-1 resistance in lung cancer." (PMID 36960400, 2023).
rheumatoid arthritis (4 papers, 2010 to 2021). A chronic, systemic autoimmune disorder characterized by inflammation in the synovial membranes and articular surfaces. "This is illustrated by increased levels of LAIR-2 in synovial fluid of patients with rheumatoid arthritis." (PMID 20730098, 2010). "Importantly, a role for LAIR-2 in systemic autoimmunity is suggested by the observation of increased LAIR-2 levels in synovial fluid of patients with rheumatoid arthritis and ankylosing spondylitis." (PMID 23691008, 2013). "Interestingly, LAIR-2 levels were demonstrated to be elevated in the joints of patients suffering from rheumatoid arthritis (RA) when compared to patients diagnosed with osteoarthritis." (PMID 23691008, 2013).
leukoplakia (3 papers, 2023 to 2025). A white patch or plaque on a mucous membrane that cannot be characterized clinically or pathologically as any other disease. "Collagen (specifically COL1A1) from fibroblasts induced the expression of LAIR2 (CD306), a soluble collagen receptor that activates pro-inflammatory processes, in leukoplakia Tregs, thus creating a favorable microenvironment for tumor progression." (PMID 38188682, 2023). "Regulatory T cells in leukoplakia and HNSCC tissues were reported to express LAIR2, providing a favorable environment for tumor growth, and updating the pathobiological insights into cell–cell interactions during the stepwise progression of H NSCCs." (PMID 41255572, 2025). "Furthermore, we report that the regulatory T cells in leukoplakia and HNSCC tissues express LAIR2, providing a favorable environment for tumor growth." (PMID 36828832, 2023).
ankylosing spondylitis (2 papers, 2013 to 2023). An autoimmune chronic inflammatory disorder characterized by inflammation in the vertebral joints of the spine and sacroiliac joints. "For instance, the LAIR-2 SNP rs2287828 has been shown to be associated with the susceptibility to ankylosing spondylitis and pemphigus diseases and was found to affect the LAIR-2 mRNA expression level." (PMID 36593237, 2023).
autoimmune disease (2 papers, 2013 to 2021). A disorder resulting from loss of function or tissue destruction of an organ or multiple organs, arising from humoral or cellular immune responses of the individual to their own tissue constituents. "Former studies also showed in autoimmune diseases, expression of LAIR2 was increased, and genetic single nucleotide polymorphism of LAIR2 was related to susceptibility of autoimmune diseases." (PMID 33841428, 2021). "In order to verify the possible role of LAIR-2 in the pathogenesis of autoimmune diseases, we investigated the presence of LAIR-2 in a group of ATD patients and controls." (PMID 23691008, 2013). "Thus, LAIR-2 may function as a pro-inflammatory mediator by decreasing the inhibitory potential of the immune inhibitor LAIR-1, resulting in enhanced activation of immune cells, a characteristic of autoimmune diseases." (PMID 23691008, 2013).
Autoimmunity (2 papers, 2013 to 2024). The occurrence of an immune reaction against the organism's own cells or tissues. "Increased LAIR-2 levels in ATD could be associated with and contribute to chronic inflammation characterizing organ-specific autoimmunity." (PMID 23691008, 2013). "However, data concerning the possible role of LAIR-2 and LAIR molecules/collagen interactions in organ-specific autoimmunity are lacking." (PMID 23691008, 2013).
cholangiocarcinoma (2 papers, 2021 to 2023). A carcinoma that arises from the intrahepatic biliary tree (intrahepatic cholangiocarcinoma) or from the junction, or adjacent to the junction, of the right and left hepatic ducts (hilar cholangiocarcinoma). "Recently, pro-nociceptin and leukocyte-associated immunoglobulin-like receptor 2 were identified as biomarkers for assessment of immune infiltration in cholangiocarcinoma using a combination of batch sequencing and single-cell sequencing." (PMID 38274109, 2023). "There were 43 genes differentially expressed between high- and low-immune infiltrated patients, and after further compression, PNOC and LAIR2 were significantly correlated with high immune infiltration status in cholangiocarcinoma." (PMID 33841428, 2021). "PNOC and LAIR2 were biomarkers for immune infiltration evaluation in cholangiocarcinoma." (PMID 33841428, 2021). "These functionally different cell populations in tumor justify the need of combining immune therapy in cholangiocarcinoma, and PNOC and LAIR2 could be clinical biomarkers for patient evaluation before immune therapy, predicting patients’ survival and tumor immune infiltration accordingly." (PMID 33841428, 2021).
lung adenocarcinoma (2 papers, 2021 to 2023). A carcinoma that arises from the lung and is characterized by the presence of malignant glandular epithelial cells. "High expression of leukocyte-associated Ig-like receptor 2 (LAIR-2), an inhibitor of immune inhibition receptor LAIR-1, in Treg is correlated with poor outcome in lung adenocarcinoma." (PMID 36906534, 2023). "In this study, we demonstrated a prognostic role for tumor infiltrating CD4+ LAIR2+ Treg cells in lung adenocarcinoma." (PMID 35008369, 2021). "LAIR2, which defines a subset of adversely prognostic Treg cells in lung adenocarcinoma, therefore provides a potential target for immunotherapeutic development." (PMID 35008369, 2021). "A CD4+ LAIR2+ Treg gene signature was prognostically significant in the TCGA dataset (n = 439; hazard ratio (HR) = 1.37; 95% confidence interval (CI), 1.05–1.77, p = 0.018) and validated in NCI Director’s Challenge lung adenocarcinoma dataset (n = 488; HR = 1.54; 95% CI, 1.14–2.09, p = 0.0045)." (PMID 35008369, 2021).
allergic disease (1 paper, 2013). An immune response that occurs following re-exposure to an innocuous antigen, and that requires the presence of existing antibodies against that antigen. "Thus, LAIR-2 is likely to play a pivotal regulatory role of LAIR-1 function on T cells This might be a quite general mechanism, and the role of LAIR-2 in diseases with chronic inflammation, including allergic diseases, is worth of investigations." (PMID 23691008, 2013).
autoimmune hyperthyroidism (1 paper, 2013). "In addition, LAIR-2 concentrations were significantly higher in patients with hyperthyroid GD than in controls with non-autoimmune hyperthyroidism (p<0.05) (MNTG)." (PMID 23691008, 2013).
dysplasia (1 paper, 2025). A usually neoplastic transformation of the cell, associated with altered architectural tissue patterns. "Interestingly, LAIR2 was one of the genes found to be upregulated in CD8+ T cells in dysplasia and EAC, suggesting that this may represent a novel immune marker in BE-associated neoplasia." (PMID 40844321, 2025).
head and neck squamous cell carcinoma (1 paper, 2021). A squamous cell carcinoma that arises from any of the following anatomic sites: lip and oral cavity, nasal cavity, paranasal sinuses, pharynx, larynx, and salivary glands. "(A) LAIR-2 overexpression is associated with improved overall survival in some tumors: head and neck squamous cell carcinoma (HNSC), thyroid carcinoma (THCA), thymoma (THYM) and skin cutaneous melanoma (SKCM)." (PMID 34121658, 2021).
hypothyroidism (1 paper, 2023). Abnormally low levels of thyroid hormone. "LncRNA-PAX8-AS1 and LAIR-2 expression profiles have the potential as effective diagnostic and prognostic indicators of hypothyroidism." (PMID 36593237, 2023). "Expression levels of serum LncRNA-PAX8-AS1 and LAIR-2 mRNA were selected as significant predictors associated with the possibilities of clinical hypothyroidism diagnosis in the univariate analysis (P < 0.05)." (PMID 36593237, 2023). "In clinical hypothyroidism, the expression levels of LncRNA-PAX8-AS1 and LAIR-2 mRNA were markedly different compared to subclinical hypothyroidism and healthy control, indicating their diagnostic value." (PMID 36593237, 2023). "Surprisingly, serum LncRNA-PAX8-AS1 and LAIR-2 mRNA expression demonstrated superior diagnostic accuracy for clinical hypothyroidism and turned out as independent predictors in the multivariate analysis." (PMID 36593237, 2023). "Therefore, this study aimed to investigate the possible role of LncRNA-PAX8-AS1 and LAIR-2 genetic variants in the development of both subclinical and clinical (overt) hypothyroidism." (PMID 36593237, 2023). "Furthermore, the serum LncRNA-PAX8-AS1 and LAIR-2 mRNA and protein levels have the potential as novel diagnostic and prognostic indicators of hypothyroidism." (PMID 36593237, 2023). "This study identified that serum LncRNA-PAX8-AS1 downregulation as well as LAIR-2 upregulation could be implicated in hypothyroidism." (PMID 36593237, 2023). "Herein, we found that the studied SNPs affected the differential gene expression of the circulating LncRNA-PAX8-AS1 and LAIR-2 mRNA coupled with its protein in hypothyroidism." (PMID 36593237, 2023). "Conclusively, LncRNA-PAX8-AS1 and LAIR-2 genetic variants are novel genetic biomarkers of hypothyroidism that could alter the LncRNA-PAX8-AS1 and LAIR-2 expression." (PMID 36593237, 2023). "This study is the first to propose the LncRNA-PAX8-AS1 and LAIR-2 variants as novel genetic biomarkers of hypothyroidism, which could alter the LncRNA-PAX8-AS1 and LAIR-2 expression." (PMID 36593237, 2023). "Importantly, several molecules were deduced to function in hypothyroidism, the lncRNA-paired-box gene 8-antisense RNA 1 (LncRNA-PAX8-AS1) and the leukocyte-associated Ig-like receptor-2 (LAIR-2) were proposed as one of the most important in such condition." (PMID 36593237, 2023). "Moreover, LncRNA-PAX8-AS1 rs4848320 and rs1110839 as well as LAIR-2 rs2287828 were functionally correlated with the serum expression levels of LncRNA-PAX8-AS1 and LAIR-2 mRNA along with its protein, respectively in hypothyroidism." (PMID 36593237, 2023). "Importantly, the analysis also revealed that serum LAIR-2 mRNA distinguished all hypothyroid group, clinical, and subclinical patients from healthy controls with a sufficient performance power (AUC = 0.8, 0.9, and 0.71, respectively) and with an excellent discrimination of clinical hypothyroidism." (PMID 36593237, 2023). "However, studies on the impact of LncRNA-PAX8-AS1 and LAIR-2 gene polymorphisms with differential expression levels on hypothyroidism are still lacking." (PMID 36593237, 2023). "Assessment of serum LncRNA-PAX8-AS1, LAIR-2 mRNA, and LAIR-2 protein levels in clinical and subclinical hypothyroid patients carrying different SNP genotypes was performed in order to study the mechanistic role of rs4848320, rs1110839, and rs2287828 in hypothyroidism." (PMID 36593237, 2023).
leukemia (1 paper, 2025). A malignant (clonal) hematologic disorder, involving hematopoietic stem cells and characterized by the presence of primitive or atypical myeloid or lymphoid cells in the bone marrow and the blood. "Further, LAIR2 might be studied as a biomarker of some leukemia therapy response or as a mechanism of resistance." (PMID 40563506, 2025).
ovarian carcinoma (1 paper, 2025). A malignant neoplasm originating from the surface ovarian epithelium. "The ongoing trial NCT05572684 using NC410 (the dimeric LAIR-2 protein fused to a human IgG1 Fc domain, see Chapter 4.1) in combination with the anti-PD1 pembrolizumab in MSS and low-microsatellite stable CRC or ovarian cancer may give some insights into the cooperation of conventional ICI and LAIR1." (PMID 40563506, 2025).
preeclampsia (1 paper, 2015). Preeclampsia is a hypertensive disorder of pregnancy that is characterized by new-onset hypertension with proteinuria presenting after 20 weeks of gestation, and depending on mild or severe forms may initially present with severe headache, visual disturbances, and hyperreflexia. "Under-expressed LAIR-2 may contribute to the failed remodeling of maternal spiral arteries in preeclampsia." (PMID 26580600, 2015). "Remaining mRNA from the microarray samples were submitted to quantitative polymerase chain reaction (qPCR) studies, demonstrating LAIR2 and FSTL3 were each lower with large effect size in preeclampsia compared with uncomplicated pregnancy, which was consistent with the microarray results." (PMID 26580600, 2015). "Although LAIR-2 protein had been detected in the urine of pregnant women, the genome-wide microarray analysis of CVS specimens was the first to identify the gene being expressed at the maternal-fetal interface in the placenta, where it was down-regulated in preeclampsia cases." (PMID 26580600, 2015).
rotator cuff tears (1 paper, 2022). "This study showed an association between the occurrence of rotator cuff tears and several genes, including LAIR2, REST, and CRIPAK." (PMID 36292186, 2022). "Through this study, we newly identified SNPs of genes LAIR2, CRIPAK, and REST that were significantly altered in patients with rotator cuff tears." (PMID 36292186, 2022).
Stroke (1 paper, 2025). Sudden impairment of blood flow to a part of the brain due to occlusion or rupture of an artery to the brain. "At the same time, HBB levels stayed high, although PSA samples from stroke patients showed significantly lower levels of LCN2, LAIR2, and RPS10." (PMID 40270596, 2025). "In particular, the three DElncRNAs (CTD-2545M3.2, RP11-24N18.1, and RP11-473C18.7) and four DEGs (LCN2, LAIR2, RPS10, and HBB) that showed the most significant variations between PSA and HC samples were selected for further qPCR verification in the samples from the HC, stroke, PSA, and PSA-T groups." (PMID 40270596, 2025).